LEP (leptin)
Diseases named in the same sentence as LEP in open-access papers (continued):
Sharing a sentence is not in itself a finding about the gene and the disease.
Obesity (continued). "Leptin knockout mice were only used to simulate the absence of leptin in vivo, though such a state never exists in obesity or NASH." (PMID 25658689, 2015). "In addition, obesity may also induce chronic low-grade inflammation resulting in an alteration of local and systemic levels of cytokines (e.g., interleukin-6, C-reactive protein) and adipokines (e.g., leptin, adiponectin), which may play a role in bladder carcinogenesis to bladder cancer mortality." (PMID 25803438, 2015). "Taken together, all these data are in accordance with our results indicating that leptin does not participate in the decreased GH secretion in obesity." (PMID 25782001, 2015). "It seems unlikely that this apparent lack of responsiveness to leptin is the result of insensitivity driven by the development of obesity." (PMID 25789758, 2015). "Obesity due to adipocyte hypertrophy leads to changes in adipocytokine profiles involved in the development of insulin resistance, as well as in the production of signaling molecules, such as PPAR-γ, aP2, and leptin." (PMID 25280587, 2014). "While the association between leptin and CRP was independent of obesity level, there was a statistically significant increase in the concentration of these markers as the level of obesity increased." (PMID 24944619, 2014). "The meta-analyses of MS and obesity markers indicated that TG, TC, CRP BMI, TBF%, WC, WHR and Leptin were positively correlated with chemerin, nevertheless, SBP, DBP, LDL-C, HDL-C, ALT and r-GT were not significantly correlated, adiponectin was negatively correlated." (PMID 25469985, 2014). "Given that leptin and CNTF play important roles in energy homeostasis and that obesity is an inflammatory condition in adipose tissue, we hypothesized that G-CSF could also play a role in energy homeostasis." (PMID 25144367, 2014). "In a recent study, mice lacking the PTP1B were protected from diet-induced obesity and were hypersensitive to leptin." (PMID 24987707, 2014). "Recent studies also showed that obesity-induced leptin functions directly in promoting the progression of non-alcoholic steatohepatitis." (PMID 24838072, 2014). "Studies from different populations have shown that indexes of obesity are predictive factors for OSA and as adipocytes are the most important source of adiponectin and leptin, it is expected that circulating leptin and adiponectin would be predictive of OSA severity." (PMID 24982545, 2014). "In obesity, expansion of white adipose tissue increases leptin levels, but the protein does not convey its biological effects." (PMID 24600449, 2014). "Both decrease in NO and increase in EDHF are corrected by leptin antagonist suggesting that they are accounted for by chronic hyperleptinemia but not by other consequences of obesity." (PMID 24475175, 2014). "Taken together, these studies shed little light on factors involved in human obesity, as leptin's effects on brain do not have the same influence on neuroendocrine or peripheral tissue effects associated with human obesity and T2DM." (PMID 24809394, 2014). "Due to single-gene mutations that lead to the lack of action by the satiety factor leptin or its cognate receptor, these rodents spontaneously develop severe hyperphagia leading to obesity and manifest some T2DM-like characteristics." (PMID 24809394, 2014). "PEG-SRLA blocks the effects of endogenous leptin but does not reduce or even aggravates other disturbances observed in obesity by reducing anorectic effect of leptin and further increasing weight gain." (PMID 25521118, 2014). "Alms1GT/GT mice had increased expression of leptin in SAT and VAT and a slight elevation of plasma leptin levels, although not statistically significant, before the onset of obesity." (PMID 25299671, 2014). "Differently, cholesterol and leptin levels increased with obesity, but were not affected by losartan administration." (PMID 24466104, 2014).
Obesity (continued). "Despite the lack of effect of dietary fructose on obesity in these mice, we tested leptin sensitivity in fructose-fed mice and found they displayed normal sensitivity to leptin." (PMID 25211467, 2014). "Furthermore, there is always a limitation in analyzing multiple factors in biological systems (e.g. leptin, CRP and obesity) due to the adjustments that have to be made for common disease pathways." (PMID 24944619, 2014). "In a Chinese study, PCOS women were characterized by higher leptin levels both in serum and follicular fluid than controls, although the BMI of the PCOS women included in this study ranged from normal-weight to overweight and obesity." (PMID 24895638, 2014). "Leptin, a 16-kDa non-glycosylated polypeptide anti-obesity hormone consisting of 146 amino acids, is a product of the obese (ob) gene." (PMID 25033454, 2014). "Plasma levels of leptin can increase as the result of obesity; in the present study we saw no changes in body weight, BMI, or WHR after 1 year." (PMID 25136143, 2014). "It is unlikely that the other gene variants with potential damaging effect also play a role in the pathogenesis of obesity, since they are not related to the regulation of the leptin-melanocortin pathway." (PMID 25158045, 2014). "Irisin could contribute to the modulation of obesity-induced inflammatory/anti-inflammatory balance by increasing CD206 and interleukin 10 and decreasing tumour necrosis factor alpha and leptin." (PMID 25530809, 2014). "Subgroup analysis taking in consideration the effect of obesity on maternal adipokine levels showed that circulating levels of TNF-α and leptin remained elevated in GDM patients compared to their body mass index (BMI) matched controls, and adiponectin level remained depressed in GDM individuals." (PMID 25202741, 2014). "Unlike leptin, adiponectin is a protective hormone whose serum levels are inversely related to obesity and insulin resistance." (PMID 24982545, 2014). "Our findings demonstrate a novel pathway that links leptin signalling and expression of oncogenic enzyme SK1 in breast tumours, which may have a physiological significance in obesity driven ER-negative breast cancer." (PMID 25482303, 2014). "Understanding the biological function of leptin and its receptor (OBR) is an important step in order to conceive efficient and specific therapeutic tools that would rescue the impaired function of the leptin system observed in obesity." (PMID 25352831, 2014). "Neither a high endogenous leptin level nor treatment with exogenous leptin is effective in ameliorating the most common form of obesity, consistent with a state of leptin resistance." (PMID 25167881, 2014). "Indeed numerous characteristics of obesity and metabolic syndrome have been observed in 36 wk old NZBWF1 mice that included increased body weight, hypertension, elevated plasma leptin, insulin resistance, and central adiposity with macrophage infiltration." (PMID 24945254, 2014). "We have previously shown that disruption of cardiac‐specific leptin signaling, but not obesity per se impairs the ability of mice to increase glycolysis in response to a cardiac ischemic hypoxic stress." (PMID 24771695, 2014). "Possible explanations underlying the discrepancy between the present and some previous studies include the animal species, as the absence of a response to leptin in obesity has been so far primarily observed in rats." (PMID 23841921, 2013). "Descriptive statistics of all study participant saliva samples tested for Bone Panel (osteoprotegrin (OPG), leptin, parathyroid hormone (PTH) and insulin), Matrix Metalloproteinase Panel (MMP-2, MMP-8, MMP-9) and Obesity Panel (adiponectin and C-reactive protein (CRP))." (PMID 23577067, 2013).
Obesity (continued). "Descriptive statistics of all study participant serum samples tested for Bone Panel (osteoprotegrin (OPG), leptin, parathyroid hormone (PTH) and insulin), Matrix Metalloproteinase Panel (MMP-2, MMP-8, MMP-9) and Obesity Panel (adiponectin and C-reactive protein (CRP))." (PMID 23577067, 2013). "The correlations of leptin with CRP and white blood cells, which were found also in the present study, confirm the implication of this peptide in sustaining the low-grade inflammation and, ultimately, β-cell dysfunction in obesity." (PMID 24454366, 2013). "Although initially promising, the discovery of the hormone leptin and its contribution to obesity in the leptin knockout mouse (ob/ob) did not prove to be a “quick fix” to the problem of obesity." (PMID 24533218, 2013). "In contrast, ob/ob mice show severe hyperphagic obesity due to the genetic absence of the satiety factor leptin." (PMID 24409114, 2013). "Given the common pathogenesis between obesity, diabetes, COPD and cancer, and the individual carcinogenesis role of cigarette smoking and leptin gene family, we inferred a possible role of the interaction between smoking and LEPR polymorphism in colorectal cancer susceptibility." (PMID 23593308, 2013). "Given that LdOp females showed no improvement in these parameters in the long term we concluded that the pre-requisites for osteoporosis result from chronic obesity rather than obesity & leptin levels during the early postnatal period." (PMID 23544111, 2013). "It is also possible that excess weight itself is correlated to lower bone mass in young age, thus causing weaker osteoclast activity and lower counteracting levels of OPG, or that obesity induces decreased osteoblast production of OPG through hormonal paths, perhaps through leptin-mediated actions." (PMID 24288529, 2013). "Our findings revealed that OB-1 had no direct effect on anti-obesity and regulation of leptin and adiponectin; however, OB-1 increased the phosphorylation of AMPK and the activity of movement in vivo." (PMID 23533517, 2013). "Further, significant higher level of leptin was found in insulin resistant subjects compared to the subjects without the condition at the same level of obesity in both gender." (PMID 23349940, 2013). "Fasting rodents with reduced leptin levels and ob/ob mice exhibit decreased level of hypothalamic POMC mRNA, which is normalized by exogenous leptin administration that subsequently improves obesity and diabetes." (PMID 23579596, 2013). "Unlike leptin, the circulating levels of adiponectin, a hormone produced predominantly by adipocytes, are decreased in obesity." (PMID 24455420, 2013). "Many of them proved that A allele carriage is connected with the higher body mass, tendency to obesity, higher body mass index, and fat tissue content, as well as higher leptin concentration in blood serum, whereas others did not confirm similar correlations." (PMID 24319457, 2013). "Children with ABO and without general obesity, have high level of Leptin and Visfatin and low level of Adiponectin which are important risk factors for metabolic syndrome in children." (PMID 24578834, 2013). "Adipokines mainly involved in obesity and MetS are leptin, nonesterified free fatty acids (NEFAs), reactive oxygen species (ROS), adipocytic angiotensinogen and resistin." (PMID 24288531, 2013). "Unfortunately, the Lep°b/Lep°b mouse is not a good general model of human obesity because it lacks leptin, and this has many downstream consequences—low sympathetic activity and high hypothalamic neuropeptide Y release, for example." (PMID 23580228, 2013). "Since the patient population analyzed in these two resources did not differentiate patients based on obesity status, it would be expected that the results presented here would reveal only a limited scope on the effects of leptin on survival rate." (PMID 24176089, 2013). "Though leptin acts on the hypothalamus to induce satiety, its role in common human obesity is not clear." (PMID 24250335, 2013).
Obesity (continued). "Obese rodents and humans generally display increased circulating leptin levels; however, despite the hyperleptinaemia, leptin often fails to cease obesity development." (PMID 23936486, 2013). "This novel finding of inhibition of LEP gene expression by COS at an epigenetic level in adipocytes can be explored for manipulation of leptin gene expression, adipogenesis, energy homeostasis and obesity." (PMID 23544120, 2013). "Studies on the role of the sympathetic nervous system in the anti-obesity effect of leptin are described in section Detection of Non-Acute Thermogenesis." (PMID 23580228, 2013). "Of note, our findings also indicate that leptin signaling is not a prerequisite to develop cardiac hypertrophy in obesity and that additional pathways also contribute to the increase in LV mass associated with higher body weight." (PMID 23841921, 2013). "Unfortunately, plasma insulin and obesity-related parameters, such as leptin and tumor necrosis factor (TNF) α, were not measured in the earlier studies." (PMID 22748134, 2012). "Therefore, these direct and indirect effects of leptin on the kidney, including stimulating cellular proliferation and hypertrophy, increasing extracellular matrix expression, and exhibiting proinflammatory activities, may partially explain obesity-related kidney disease." (PMID 22567283, 2012). "Leptin significantly results in the phosphorylation of p70S6K and p90 ribosomal S6 kinase 1 (RSK1) in mice placed on a low-fat diet and leads to hyperphagia, weight gain, and leptin resistance during diet-induced obesity." (PMID 23203037, 2012). "Whichever strategy is chosen, it should not modify the influence of leptin on food intake in order to avoid the development of hyperphagia and obesity." (PMID 22584415, 2012). "It has been known that leptin circulates at levels directly proportional to body fat; however, in boys, FAT% measured in our study did not decrease like leptin, but was stable during puberty even in those overweight or obesity." (PMID 23316228, 2012). "In addition, a lower expression of ObRb in the ARC of IUGR versus control piglets was observed suggesting a lower sensitivity to leptin action in IUGR leading to altered food intake behaviour and subsequent obesity." (PMID 23251802, 2012). "Adipokine hormones such as leptin have long been thought to contribute to OA pathogenesis directly, independent of the mechanical effect of obesity." (PMID 22651805, 2012). "In contrast to leptin, adiponectin has a strong negative correlation with fat mass, decreasing in concentration during obesity and insulin resistance and increasing in concentration during weight loss." (PMID 23146593, 2012). "Leptin can control the production and activation of pro-inflammatory cytokines such as IL-6 and TNF-α by macrophages, and is a key regulatory factor expressed in both zebrafish and mammalian obesity in lipid metabolism." (PMID 22947075, 2012). "Our model produces a low-grade peripheral inflammation without obesity where hyperleptinemia is present and there is a correlation between leptin and several interleukins with peripheral insulin resistance." (PMID 23056516, 2012). "We included leptin a 16 kDa nonglycosylated polypeptide, referred to as the obesity hormone, which plays an important role in the regulation of body fat." (PMID 23056045, 2012). "It is important to note that resistance to obesity in these animals is dependent on increased leptin sensitivity and is therefore absent in mice additionally lacking leptin." (PMID 22829877, 2012). "Authors conclude that in adipocytes AR plays an inhibitory role in leptin production, but lack of androgens signalling in the adipocyte is not sufficient to promote obesity." (PMID 22235202, 2012). "Waist circumference reflects abdominal visceral adipose tissue accumulation, and chest circumference is a measure of upper body obesity that exhibits relationships to plasma leptin levels that are not apparent for waist or hip measurements." (PMID 22384023, 2012).
Obesity (continued). "By contrast, the lower serum amylase levels in lean and obese subjects in the high leptin and high HOMA-R groups suggests that severe insulin resistance exceeding a threshold level may predict low serum amylase, independently of obesity." (PMID 22748134, 2012). "High leptin levels were associated with a more severe disease suggesting that the link between leptin and asthma is not restricted to obesity." (PMID 21615949, 2011). "The lack of correlation of the tested genes and obesity in ALL survivors together with changes in leptin/soluble leptin receptor plasma levels suggest, that influence of the selected genetic polymorphisms was not very potent." (PMID 21631924, 2011). "The results revealed that the obesity-promoting effect of HIF loss-of-function remained in ob/ob mice, indicating that leptin signaling was not involved in the metabolic action of hypothalamic HIF." (PMID 21814490, 2011). "We also sought to determine if leptin induced increases in total locomotor activity are independent of changes in body weight and obesity." (PMID 21853117, 2011). "Assuming simple linear pathways as the causal explanation of disease has produced neither promising preventive strategies nor effective drug treatments for obesity, as the leptin story shows." (PMID 21276254, 2011). "The significant reduction in circulating leptin following 1 to 4 days of nCPAP therapy suggests that OSAHS itself may stimulate, at least in part, leptin production independently of obesity." (PMID 21040518, 2010). "In obesity conditions, hypothalamic resistance to leptin has been found and ascribed to reduced transport of leptin across the blood-brain barrier and to increased levels of SOCS-3 and ER stress, which inhibit leptin signaling." (PMID 20671929, 2010). "We show that mice whose plasma leptin has been clamped to lean levels develop obesity in response to a high-fat diet, and the magnitude of this obesity is indistinguishable from wild-type controls." (PMID 20613882, 2010). "The release of leptin and FABP-4 by fat cells is also enhanced in human obesity." (PMID 20508843, 2010). "Interest in leptin as anti-obesity drug decreased when elevated levels were noted in the majority of obese individuals." (PMID 27713245, 2010). "The aim of this study was to investigate the biological actions regulated by leptin, the obesity biomarker molecule, and its receptors in HCC and the correlation between leptin and human telomerase reverse transcriptase (hTERT), a known mediator of cellular immortalization." (PMID 20723213, 2010). "This is not the case, as a result of the increased leptin resistance that is observed in patients with common obesity." (PMID 21070531, 2010). "In other words, the positive associations with leptin level were independent of measures of adiposity, and obesity and leptin appear to have independent roles in breast carcinogenesis, as our earlier observation on adiponectin–breast cancer association." (PMID 19223908, 2009). "CA3 expression was decreased by leptin but increased by insulin in freshly isolated rat adipose cells, which suggests that the decrease in CA3 expression observed in obesity may be related to hyperleptinemia." (PMID 19689798, 2009). "In the present study we did not observe differences of serum concentrations of TNF-α, IL-6, and leptin between depressive and nondepressive patients with obesity." (PMID 19587822, 2009). "We found that leptin levels are clearly elevated in OSA patients (mean basal value = 12.1 ± 12.2 ug/L; men normal range: 3.8 ± 1.8 ug/L) but these levels do not correlate with OSA severity when considering confounders as obesity and fat distribution." (PMID 18828917, 2008). "Since reduced SOCS3 expression in the Arc would tend to increase signaling by leptin and other cytokines to promote leanness, the regulation of hypothalamic SOCS3 expression by STAT5 is also unlikely to underlie the obesity of the Stat5fl/fl; Nestin-Cre mice." (PMID 18286195, 2008).